RHOA (ras homolog family member A)
Diseases named in the same sentence as RHOA in open-access papers (continued):
Sharing a sentence is not in itself a finding about the gene and the disease.
T-cell lymphomas (17 papers, 2012 to 2025). "Mutated RhoA G17V is apparent in numerous CD4+ T cell lymphomas characterized by a follicular helper T cell (Tfh) like immune-phenotype." (PMID 31319592, 2019). "We transfected the T-cell lymphoma cell lines HH and HuT78 to stably express the RHOA-G17V variant." (PMID 37370838, 2023). "Interestingly, the most frequent RHOA mutant (G17V) found in human T-cell lymphoma is a loss-of-function mutation that acts as a dominant negative mutant." (PMID 31248017, 2019). "On the contrary, fast cycling P29S, P29L, and P29Q mutations in Rac1 have been identified by high‐throughput sequencing of clinical human cancers 104, 105, 106, the G17V RhoA mutation frequent found in T cell lymphomas 107, 108 and the Y42C RhoA mutation recurrently in diffuse gastric cancer." (PMID 29749605, 2018). "The cytoplasmic tail of CD47 engages with AKAP13, a RhoA-specific guanine nucleotide exchange factor, to activate RhoA and increases the growth and metastasis of T cell lymphoma in vivo." (PMID 39039207, 2024). "For example, the RhoA-G17V mutation leading to increased activation of the RhoA-GEF Vav1 and a gain-of-function mutation in the RhoA-GEF Vav1 itself leading to increased RhoA activation, are found in T-cell lymphomas." (PMID 33906663, 2021). "The RhoA driver mutation G17V, which disrupts GTP binding, is frequently identified in T-cell lymphoma and studies in Dictyostelium cells demonstrate that phosphorylation of RhoA-GDP at S192 leads to increased mTORC2 activity and phosphorylation of AKT." (PMID 32309283, 2020). "Consistent with previous studies, inhibition of ITK also suppressed the migration and invasion of malignant T-cell lymphoma through directly inhibiting RhoA and FAK." (PMID 30814910, 2019). "LPA has also been shown to substitute for serum to markedly induce the invasion of T cell lymphoma cells through a fibroblast monolayer in a RhoA and PLC-dependent manner." (PMID 25003200, 2014). "In contrast, most T-cell lymphomas share morphological similarities and feature different frequencies of genetic alterations that either amplify the T-cell receptor signaling (e.g., NF-kB, RhoA, GATA3) or bypass it entirely (e.g., JAK/STAT, Pi3K)." (PMID 36605429, 2022). "In one case of NLPHL with slightly atypical and expanded intranodular T-cells, the detection of a classic RHOA and TET2 mutation provided definitive evidence of an associated T-cell lymphoma (which could be classified as nodal T-cell lymphoma with TFH-phenotype)." (PMID 37664054, 2023). "In addition, a fraction of T cell lymphoma samples that was negative for the RhoA G17V mutation displayed gain-of-function mutations of Vav1." (PMID 31319592, 2019). "To gain further insight into the origin of the G17V RHOA mutation, we examined the mutation in laser-microdissected PD1+ and CD20+ B cells, which were assumed to be enriched and depleted in tumor cells, respectively, in 10 nodal T-cell lymphomas (1 nodal PTCL with TFH phenotype and 9 AITL cases)." (PMID 28157189, 2017). "The T-cell lymphoma panel showed no mutations in RHOA, TET2, DNMT3A, IDH2, and other genes typically altered in TFH-derived and other T-cell lymphomas in both lymph node and BM specimens, further supporting the diagnosis of NMZL." (PMID 41515931, 2025).
T-cell lymphomas (continued). "Conversely, no mutations were found in RHOA, IDH2, and CD28, known to occur in angioimmunoblastic T-cell lymphoma and other nodal T-cell lymphomas of T follicular helper origin." (PMID 31028364, 2020). "The G17V RHOA mutants could not be converted to an active GTP-bound form, although the downstream signaling of the G17V RHOA mutants in nodal T-cell lymphomas development has yet to be clarified." (PMID 28157189, 2017).
lung adenocarcinoma (16 papers, 2012 to 2025). A carcinoma that arises from the lung and is characterized by the presence of malignant glandular epithelial cells. "Hence, this suggested that the inhibition of lung adenocarcinoma cell motility in StarD13-depleted cells could be through the indirect inhibition of Rac1, caused by the constitutive activation of RhoA." (PMID 32900380, 2020). "In agreement with our findings, the activation of RhoA/ROCK signaling has been identified as a central mechanism by which PDPN + CAFs promote tumor formation in lung adenocarcinoma." (PMID 40842027, 2025). "Concurrently, another investigation posited that ALPL specifically mitigates lung adenocarcinoma (LUAD) cell metastasis by interacting with the p-ERK/c-Myc/RhoA signaling axis." (PMID 38915066, 2024). "For example, we determined a higher editing level in the coding region of RHOA in resistant samples relative to sensitive samples in the Cisplatin‐treated lung adenocarcinoma (LUAD) samples (LUAD‐Cisplatin)." (PMID 36912579, 2023). "In lung adenocarcinoma, podoplanin expression in CAFs predicts poor prognosis, and podoplanin-expressing CAFs promote cancer cell invasiveness via RhoA activation in lung adenocarcinoma." (PMID 37993428, 2023). "The ERK-RAS Homolog Family Member A (RHOA) -FAK pathway is necessary to maintain KRAS-mutant lung adenocarcinoma." (PMID 34012925, 2021). "Collectively this data confirms that StarD13 is a tumor suppressor in lung adenocarcinoma and uncovers a RhoA-dependent mechanism for regulating cell migration and adhesion." (PMID 32900380, 2020). "To this aim, we transfected StarD13-depleted lung adenocarcinoma cells with a constitutively active RhoA or a constitutively active Cdc42 construct." (PMID 32900380, 2020). "Here, we demonstrated that Crk induced EMT in A549 human lung adenocarcinoma cells through differential regulation of Rac1/Snail and RhoA/Slug, leading to decreased expression of E-cadherin and increased N-cadherin, fibronectin, and MMP2 expression." (PMID 27027347, 2016). "Using this network, the authors constructed a CRISPR double-knockout library of RAS interactor genes and identified a synthetic lethal interaction of Rap1 GTPase-GDP dissociation stimulator 1 (RAP1GDS1) with ras homolog family member A (RHOA) in KRAS-mutant lung adenocarcinoma." (PMID 38275900, 2024). "Therefore we sought to elucidate the mechanism through which the StarD13/RhoA/Rac1 pathway regulates cell migration in lung adenocarcinoma cells, by examining its effects on cell adhesion dynamics." (PMID 32900380, 2020). "Here, our results suggested that thapsigargin may also down-regualte mTOR kinase activity and inhibit RhoA protein level in A549 human lung adenocarcinoma cells." (PMID 24605059, 2014). "Our study shows that aPC, through EPCR-PAR1-driven activation of RhoA-ROCKII-JNK1/2-MLC2 signaling, triggers extracellular vesicle (EV) release from lung adenocarcinoma cells." (PMID 41271627, 2025). "In lung adenocarcinoma, CNTN1 plays a key role in mediating metastasis and invasion through the stimulation of Ras homolog gene family, member A (RhoA)." (PMID 29673312, 2018).
Cerebral ischemia (15 papers, 2015 to 2025). Restriction of arterial blood supply to the brain associated with insufficient oxygenation to support the metabolic requirements of the tissue. "The RhoA-ROCK signaling pathway is associated with the protective effects of hydrogen sulfide (H2S) against cerebral ischemia." (PMID 35889443, 2022). "It was well-known that inhibition of the RhoA-ROCK signaling pathway protects cerebral ischemia-reperfusion injury." (PMID 35889443, 2022). "Cerebral ischemia leads to structural damage of the cytoskeleton mediated by RhoGTPasas imbalance, Ras homolog family member A (RhoA) activation, and inactivation of Ras-related C3 botulinum toxin substrate (Rac), related to the rupture of adhesion." (PMID 34064670, 2021). "Taken together, our results indicate that SC exerts anti-inflammatory and anti-oxidative effects post cerebral ischemia-reperfusion through inhibiting the RhoA-ROCK signaling." (PMID 32240450, 2020). "After cerebral ischemia, RhoA expression increases in the brain, strengthening the polymerization of actin in the growth cone and driving axial stretch to cause synaptic contraction of dendritic and spinous processes in nerve cells." (PMID 32400219, 2020). "RhoA signaling plays an important role under pathological conditions, such as cerebral ischemia reperfusion injury and axon remodeling." (PMID 27966582, 2016). "Notably, previous studies have investigated the effects of RhoA/ROCK/MLC2 in blood-brain barrier injury after cerebral ischemia/reperfusion." (PMID 35170371, 2022). "Our research shows that RhoA activity is increased in excitotoxic death processes, and inhibiting this activity reduces markers of neurodegeneration as well as improves learning and memory processes in cerebral ischemia." (PMID 25884826, 2015). "Likewise, in a cerebral ischemia/reperfusion model, AOAA blocked the neuroprotective effects of total rhododendron flavones (TFR), which act by inhibiting reactive astrogliosis and the rhoa/rho-associated protein kinase (RhoA/ROCK) signaling pathway." (PMID 41465271, 2025). "In addition, as a RhoA/ROCK downstream signaling factor, activation of myosin light chain 2 (MLC2) was produced in the form of phosphorylation, and papers have demonstrated the involvement of RhoA/ROCK/MLC2 in cerebral ischemia-reperfusion injury to the blood-brain barrier." (PMID 35170371, 2022). "In conclusion, oxycodone relieved permeability damage and apoptosis of OGD/R-induced brain microvascular endothelial cells through RhoA/ROCK/MLC2 signal, suggesting that oxycodone might be an effective method for the improvement of cerebral ischemia-reperfusion injury." (PMID 35170371, 2022).
Insulin resistance (15 papers, 2013 to 2025). Increased resistance towards insulin, that is, diminished effectiveness of insulin in reducing blood glucose levels. "Pharmacological inhibition of AKT1 or RhoA led to improved glucose intolerance and insulin resistance." (PMID 36918564, 2023). "The phosphorylation of RhoA was decreased in palmitate-induced insulin resistance, but was only marginally decreased in TNF-α induced insulin resistance." (PMID 35055191, 2022). "In murine diabetic tissues, expression of ANXA1 is decreased allowing for the activation of RhoA, while treatment with hrANXA1 inhibits RhoA activity, decreases insulin resistance, and restores Akt and eNOS signaling." (PMID 30972066, 2019). "Furthermore, activation of the RhoA GTPase, which regulates glucose uptake through cytoskeletal rearrangements, differed in iMyos cells in an insulin resistance and sex-dependent manner, in line with altered phosphorylation of RhoA regulators." (PMID 37248992, 2023). "In conclusion, our results uncovered that statins inhibit GGPP production and induce insulin resistance in skeletal muscle cells through RhoA geranylgeranylation‐mediated insulin signalling‐dependent way and RAB8A geranylgeranylation‐mediated insulin signalling‐independent way." (PMID 35961942, 2022). "RhoA and its downstream effector, Rho-kinase (ROCK), are involved in the development of insulin resistance, regulation of insulin action and glucose homeostasis." (PMID 23776620, 2013). "Mechanistically, downstream of RhoA/ROCK-mediated F-actin assembly, nuclear translocation of MRTF-A suppresses the expression of IRS1 and PPARγ in hypertrophic adipocytes, contributing to adipocyte dysfunction and insulin resistance." (PMID 35769086, 2022). "This increases RhoA/ROCK signaling and chronic mTOR activation resulting in insulin resistance." (PMID 23776620, 2013).
angioimmunoblastic T-cell lymphoma (14 papers, 2014 to 2026). A mature T-cell non-Hodgkin lymphoma, characterized by systemic disease and a polymorphous infiltrate involving lymph nodes and extranodal sites. "The aim of this study was to understand if the presence of a RHOA-G17V mutation in angioimmunoblastic T-cell lymphoma is responsible for the typical clinical presentation with early dissemination of tumor cells." (PMID 37370838, 2023). "Both TET2 and RHOA mutations, in particular, are common in angioimmunoblastic T-cell lymphoma (~ 60–70%)." (PMID 33160401, 2020). "One of the two cases of angioimmunoblastic T-cell lymphoma demonstrated known pathogenic mutations in RHOA and FYN, proteins involved in T-cell motility and proliferation and TCR signaling." (PMID 27203213, 2016). "In addition, RhoA is potentially highly mutable as frequent RhoA mutations have been found in a wide variety of human cancers, especially in angioimmunoblastic T-cell lymphoma (53–71%) and diffuse gastric cancer (14–25%)." (PMID 36555100, 2022). "RhoA mutations were identified in over half of angioimmunoblastic T cell lymphomas." (PMID 34733886, 2021). "RHOA is mutated in numerous hematopoietic malignancies, but its most significant point mutation is seen at G17V which is strongly associated with angioimmunoblastic T-cell lymphoma (AITL), found in approximately 70% of cases and peripheral T-cell lymphomas with follicular helper phenotype." (PMID 33801781, 2021). "Mutant RhoA G17V is a clinically significant yet historically undruggable oncogenic GTPase that drives angioimmunoblastic T-cell lymphoma through a neomorphic interaction with the guanine nucleotide exchange factor Vav1." (PMID 41986244, 2026). "For example, RHOA and TET2 mutations are frequently detected in angioimmunoblastic T-cell lymphoma (AITL) and IDH2R172 variant appears to be a unique mutation in AITL." (PMID 33546774, 2021). "Although RhoA is mutated less frequently than Ras genes in cancer cells, it has been shown to be altered in certain malignancies, including angioimmunoblastic T-cell lymphoma (AITL) and adult T-cell leukemia/lymphoma (ATL), highlighting its context-dependent oncogenic potential." (PMID 41002403, 2025).
COVID-19 (14 papers, 2021 to 2025). A disease caused by infection with severe acute respiratory syndrome coronavirus 2. "Recently, RHOA has been identified as one of the key hub genes involved in the immunopathogenesis of COVID-19." (PMID 40371107, 2025). "It has been confirmed in our study that FX06 reduces the upregulated RhoA expression induced by COVID-19-triggered cytokines." (PMID 40612940, 2025). "For example, ARDS and ALI in patients with severe COVID-19 were directly associated with increased expression of the PTEN and RHOA hub-high traffic genes, respectively." (PMID 34975885, 2021). "In the lungs, COVID-19 causes lung dysfunction by regulating the expression of SRC, RHOA, CD40LG, CSF1, and TNFRSF1A." (PMID 34504502, 2021). "All three Rho GTPases, RHOA, CDC42, and RAC1, showed a significant decrease in gene expression upon age in COVID-19 patients (p-trend decreasing = 0.002, p-trend decreasing = 0.008, p-trend decreasing = 0.004, respectively)." (PMID 34696514, 2021). "Next, we tested whether RhoA/ROCK activation might mediate HA fragment–induced barrier disruption in lung endothelium by culturing LMVECs in the presence or absence of a ROCK inhibitor (Y27632 ) prior to treatment with either biosynthetic HA4k or COVID-19 HA fragments." (PMID 34314391, 2021). "In the validation dataset, we found consistent metabolic trends in T cells; namely, we found that COVID-19 T cells downregulate key mitophagy genes FUNDC1, PINK1, and CSNK2B and upregulate key Rho GTPase genes RHOA, RHOBTB1, and ARAP3 as well as MTOR compared to HIV-1+ individuals." (PMID 36992700, 2023). "COVID-19 patients showed alterations in KPNA3, KPNA5, KPNA7, KPNB1, RHOA, and CDC42 expression compared with non-COVID-19 patients." (PMID 34696514, 2021). "Results show that RHOA and CDC42 expression was significantly decreased (p = 0.0036, p = 0.0044, respectively) in COVID-19 compared with non-COVID-19 patients (B.I)." (PMID 34696514, 2021).
Parkinson disease (14 papers, 2014 to 2025). A progressive degenerative disorder of the central nervous system characterized by loss of dopamine producing neurons in the substantia nigra and the presence of Lewy bodies in the substantia nigra and locus coeruleus. "RhoA/ROCK signaling has very recently also been linked to L-DOPA-induced dyskinesia in a rat model of Parkinson’s disease." (PMID 35563826, 2022). "Furthermore, a role of aberrant RhoA signaling involved in multiple neurodegenerative disease such as AD, Parkinson’s disease, and Huntington’s disease." (PMID 37388929, 2023). "In addition to atrial fibrillation, the HSR suppressive effects of RhoA are thought to contribute to disease progression in age-related neurodegenerative diseases such as Alzheimer’s and Parkinson’s disease." (PMID 26193369, 2015). "Seeing as therapeutic modulation of the RhoA/ROCK pathway also improves disease phenotypes in neurodegenerative models such as amyotrophic lateral sclerosis and Parkinson's disease, the perturbed GC-KLF15-BCAA activity may not be limited to SMA and DMD." (PMID 29735415, 2018).